FGF8 (fibroblast growth factor 8)
Diseases named in the same sentence as FGF8 in open-access papers (continued):
Sharing a sentence is not in itself a finding about the gene and the disease.
breast cancer (continued). "FGF8 signalling increases oestrogen-induced breast cancer cell proliferation by inducing the expression of the ER mRNA, and at the same time suppresses the inhibition of mitosis by activating the cell cycle regulator CDC2 and other regulators of cell cycle entry." (PMID 35193394, 2022). "These adverse characteristics mainly depend on the biological role described for FGF8, which comprises the induction of the migration and invasion capacity of cancer cells and has been tested both in vitro and in vivo in colorectal and breast cancer." (PMID 32824198, 2020). "FGF8 may also be involved in ectopic bone and cartilage formation by breast cancer cells that produce high amounts of FGF8." (PMID 18699993, 2008). "Previous work has shown that FGF8 is expressed by prostate and breast cancer cell lines." (PMID 11953856, 2002). "FGF8 expression has also been shown in a proportion of breast cancers and normal breast tissues." (PMID 11953856, 2002). "Transgenic mice in which FGF8 was expressed under an MMTV promoter developed breast cancer over a period of months implying that FGF8 may be able to promote breast cancer in mice." (PMID 11953856, 2002). "FGF8 was originally isolated from the conditioned medium of an androgen dependent mouse mammary carcinoma line (SC-3) as an androgen induced growth factor (AIGF) and was later assigned as a member of the fibroblast growth factor family on the basis of structural similarity." (PMID 11953856, 2002). "In breast cancer, HBXIP interacting with CREB can induce FGF8 promoter activity, leading to the initiation of FGF8 transcription and expression." (PMID 39766329, 2024). "For instance, they promote cell proliferation by upregulating fibroblast growth factor 8 (FGF8) and downregulating thrombospondin 1 (TSP1) expression in S115 mouse mammary tumor cells." (PMID 37681860, 2023). "Both FGF8 and FGF18 have a role in regulating the cell cycle of breast cancer cells, a finding that deserves further investigation in the search for novel potential treatments for patients with highly proliferative breast cancer." (PMID 35193394, 2022). "There have been no reports about FGF8 in CRC, but aberrant expression of FGF8 has been observed in several other cancers, especially in hormone-responsive tumors such as prostate and breast cancer." (PMID 25473897, 2015). "We also cultured human MCF-7 breast cancer cells, which do not have high endogenous FGF-8 expression, in the presence of exogenous FGF-8b." (PMID 23185502, 2012). "Following our finding that fibroblast growth factor 8 mRNA expression is increased in breast cancer, we have undertaken an immunohistochemistry study of fibroblast growth factor 8 expression in a series of human breast tissues and other normal tissues." (PMID 11953856, 2002).
Kallmann syndrome (12 papers, 2009 to 2025). Kallmann syndrome (KS) is a developmental genetic disorder characterized by the association of congenital hypogonadotropic hypogonadism (CHH) due to gonadotropin-releasing hormone (GnRH) deficiency, and anosmia or hyposmia (with hypoplasia or aplasia of the olfactory bulbs). "For example, variants in FGF8 are mainly found in patients with Kallmann syndrome (KS), and VACTERL patients with detectable FGF8 variants have bilateral cryptorchidism, a key phenotype in KS." (PMID 40692799, 2025). "According to these authors’ assessment, mutations in KAL1 appear in about 8% of cases of Kallmann syndrome, FGF8 and FGFR1 both appear in about 10% of cases and mutations both in PROKR2 or PROK2 are responsible for about 9% of cases." (PMID 32722328, 2020). "FGF8 mutations are associated with Kallmann syndrome and have more recently been described in association with recessive HPE, craniofacial defects, and hypothalamo-pituitary dysfunction." (PMID 33634051, 2020). "In humans, Fgf8 point mutations cause Kallmann syndrome (KS), a form of congenital hypogonadotropic hypogonadism (HH) that is associated with anosmia." (PMID 27656162, 2016). "Heterozygous mutations and deletions of the FGFR1/FGF8 system account for approximately 10% of Kallmann's syndrome and normosmic idiopathic hypogonadotropic hypogonadism." (PMID 22229029, 2012). "FGF8 and FGFR1 deficiency is associated with Kallmann Syndrome (KS), a congenital disease characterized by hypogonadotropic hypogonadism and anosmia." (PMID 36619551, 2022). "Genetic mutations implicated in Kallmann syndrome (KS), such as KAL1, FGFR1, PROKR2, and FGF8, have also been recently identified in patients with SOD." (PMID 33634051, 2020). "Thus far, FGFR1 and FGF8 gene variants have been identified to be causative genes not only for Kallmann syndrome, but also for CPHD, septo-optic dysplasia and holoprosencephaly." (PMID 35805171, 2022). "Indeed, FGF8 and FGFR1 deficiency severely compromises vertebrate reproduction in mice and humans and is associated with Kallmann Syndrome (KS), a congenital disease characterized by hypogonadotropic hypogonadism associated with anosmia." (PMID 31361780, 2019). "Inactivating mutations of this receptor and one of its ligands, fibroblast growth factor 8 (FGF8), have been described in patients with variable degree of hypogonadism mainly with and in few cases without anosmia." (PMID 22229029, 2012). "In humans, mutations in FGF8 and FGFR1 are known to cause congenital hypogonadotropic hypogonadism (CHH) without or with anosmia, i.e. CHH+anosmia, septo-optic dysplasia or combined pituitary hormone deficiency, Hartsfield syndrome, holoprosencephaly and split hand/foot malformation." (PMID 35833364, 2022).
colorectal cancer (8 papers, 2015 to 2024). A primary or metastatic malignant neoplasm that affects the colon or rectum. "Recently, we could show that the expression of FGF8 was strongly associated with the regression grade in neoadjuvantly treated colorectal cancer patients." (PMID 31527546, 2019). "Furthermore, a high level of FGF8 expression was more likely to be associated with poor outcome in patients with T1/2stage colorectal carcinoma (middle) compared to those with T3/4 stage disease (right)." (PMID 25473897, 2015). "High expression of FGF8 has been implicated in promoting EMT and tumorigenesis in oral squamous carcinoma cells and in colorectal cancer." (PMID 37222403, 2023). "FGF8 was elevated in colorectal cancer tissues, and high FGF8 expression in colorectal cancer cells led to EMT marker expression, enhanced proliferation and invasion, and in vivo tumor growth and metastasis in a YAP1-dependent manner." (PMID 33801580, 2021). "This goes in good accordance with published data: overexpression of androgen related FGF8 is known to play a crucial role in prostate and colorectal cancer." (PMID 31527546, 2019). "In a previous study, we reported that activation of FGF8 contributed to metastasis and poor prognosis in patients with colorectal cancer." (PMID 28880263, 2017). "In this current study, mild immunoreactivity for FGF8 was observed in colorectal cancer cases, and is significantly correlated with lymph node metastasis and poor prognosis." (PMID 25473897, 2015). "Immunohistochemistry staining was further performed on a panel of 98 colorectal cancer specimens and 42 matched adjacent normal colorectal mucosa specimens to investigate the potential clinical role of FGF8 in CRC." (PMID 25473897, 2015). "FGF8 was found to impart proliferative and metastatic capacity of colorectal cancer cells." (PMID 30079292, 2018). "Nuclear-YAP1 and FGF8 levels were plotted against each other, and the staining of nuclear YAP1 in high-FGF8-expressing tumors was stronger than that in low-FGF8-expressing tumors, suggesting that the expression of YAP1 is associated with FGF8 level in colorectal cancer." (PMID 25473897, 2015). "In colorectal cancer, YAP1-mediated activation of FGF8 transcription led to overexpression of FGF8." (PMID 39766329, 2024). "In both early-stage (T1/2) and late-stage (T3/4) colorectal carcinoma, FGF8 expression was much higher in the primary CRC tissue from individual patients with metastatic lymph nodes compared to those without metastatic lymph nodes, suggesting FGF8 is involved in metastasis of CRC." (PMID 25473897, 2015).
holoprosencephaly (8 papers, 2012 to 2025). Holoprosencephaly (HPE) is a complex brain malformation resulting from incomplete cleavage of the prosencephalon, occurring between the 18th and 28th day of gestation, and affecting both the forebrain and face, which results in neurological manifestations and facial anomalies of variable severity. "For a FGF8 sporadic missense variant, brain MRI identified lobar holoprosencephaly, supporting the pathogenicity of the variant and leading to ToP because of the poor neurodevelopmental prognosis." (PMID 37035737, 2023). "For example, for the FGF8 missense variant, brain MRI subsequently confirmed complete lobar holoprosencephaly, further confirming the pathogenicity of the variant." (PMID 37035737, 2023). "The first recessive mutation in the Fgf8 gene appeared in a patient with semilobar holoprosencephaly associated with diabetes insipidus and deficiencies in the pituitary hormones ACTH and TSH." (PMID 33324176, 2020). "However, only 25% of holoprosencephalic cases are due to mutations in known genes correlated with holoprosencephaly (e.g., Shh, Fgf8, Six3), leaving 75% of cases with unknown mutations." (PMID 33324176, 2020). "Many of the altered genes, including BMP4, FGF8, SIX3 and LHX2, have previously been associated with PAE and phenotypes of FASD, like defects in heart and corpus callosum development as well as holoprosencephaly." (PMID 40401629, 2025). "These Fgf8 mouse mutants also show features reminiscent of agnathia and holoprosencephaly, which are also found in patients with first arch syndromes." (PMID 31471293, 2019). "Previous data in the literature indicated that reducing FGF8 signalling in the telencephalon leads to severe brain phenotypes, and in particular to holoprosencephaly and Fgf8 hypomorphic mutants show corpus callosum defects." (PMID 22479201, 2012). "Furthermore, FGF8 and SIX3 have been found to be mutated in holoprosencephaly (HPE), a common developmental defect in midline patterning of the forebrain and/or midface." (PMID 40401629, 2025).
hypospadias (7 papers, 2019 to 2025). Hypospadias is the displacement of the urethral meatus on the ventrum of the penis. "Sonic hedgehog (Shh) mutants result in hypospadias associated with increased cell death and failure to maintain Wnt-Fgf8 signaling in endoderm." (PMID 31558700, 2019). "Significant alterations in DNA methylation of sex hormone receptor genes (ESR1 and AR) and fibroblast growth factor (FGFR2 FGF8) may correlate with abnormal expression of these genes in patients with hypospadias." (PMID 39959693, 2025). "Fgf8, Fgf10, and their receptor Fgfr2 were identified as candidate genes for human hypospadias." (PMID 40072077, 2025). "And FGF17 has high homology to FGF8, while FGF8 signaling is required for genital tubercle (GT) proximal-distal outgrowth, as abolishing FGF8 or its receptors leads to GT agenesis in mice, resulting in hypospadias." (PMID 35669683, 2022). "Several FGF genes, including FGF8, FGF10, and fibroblast growth factor receptor 2 (FGFR2), were found to be expressed in the foreskin of children with hypospadias." (PMID 40072077, 2025).
cleft lip (6 papers, 2009 to 2023). Congenital defect in the upper lip where the maxillary prominence fails to merge with the merged medial nasal prominences. "FGFs, Sprouty Homolog 1 (Spry1), and Spry2 in Fgf-8 are also involved in craniofacial development and associated with cleft lip or palate." (PMID 36995541, 2023). "In a DNA sequencing study, an individual with bilateral cleft lip and palate was identified with a de novo FGF8 mutation." (PMID 31471293, 2019). "In a human genetic study on non-syndromic cleft lip and palate, an individual with bilateral CL/P was found carrying a missense mutation in the FGF8 gene." (PMID 31471293, 2019). "Some specificities were observed such as one patient presenting with a history of cleft palate, cleft lip and a normal sense of smell, suggesting a mutation of fibroblast growth factor receptor 1 (FGFR1) or a mutation in FGF8." (PMID 31448010, 2019).
hepatocellular carcinoma (6 papers, 2016 to 2021). A malignant tumor that arises from hepatocytes. "In hepatocellular carcinoma, FGF8 subfamily members, including FGF8, FGF17 and FGF18, were upregulated to facilitate cell survival and angiogenesis via activating ERK." (PMID 30082912, 2019). "Recently, our group investigated the role of FGF8, FGF18, and FGFR4 in colo-(rectal) and hepatocellular cancer." (PMID 31527546, 2019). "FGF8 and FGF10 are involved in embryonic liver development, FGF7 and FGF9 in repair in response to liver injury, and FGF5, FGF8, FGF9, FGF17, and FGF18 in the development and progression of hepatocellular carcinoma." (PMID 27148532, 2016). "In addition, FGF5, FGF8, FGF9, FGF17, and FGF18 play roles as paracrine signals in the development and progression of hepatocellular carcinoma." (PMID 27148532, 2016). "Overexpression of FGFs was reported, for instance, for FGF8 and FGF19 in hepatocellular carcinoma (HCC) and for FGF2 in multiple cancers including melanoma and mesothelioma." (PMID 29152117, 2017).
hypogonadotropic hypogonadism (6 papers, 2010 to 2025). Abnormal ovarian or testicular function due to insufficient hormonal stimulation from the hypothalamic-pituitary axis. "Recently, a sequencing screen in individuals with congenital hypogonadotropic hypogonadism was applied to search for mutations within the FGF8 synexpression group." (PMID 33670044, 2021). "Congenital central hypogonadism is believed to be caused by genetic pathogenic variants, with genes such as ANOS1, FGFR1, FGF8, PROKR2, and PROK2 being implicated." (PMID 39817151, 2025). "Moreover, while a decrease in FGF8 signalling has been related to hypogonadotropic hypogonadism in human and mice, a similar syndrome was characterized in Klotho-deficient mice." (PMID 20844315, 2010). "Additionally, genetic causes of isolated hypogonadotropic hypogonadism such as KAL1, FGFR1/FGF8, PROKR2/PROK2, CHD7, or GNRH1 gene mutations have not been studied because the patient had a normal puberty and regular menstruation before the amenorrhea." (PMID 26266058, 2015).
CHARGE syndrome (5 papers, 2013 to 2020). CHARGE syndrome is a multiple congenital anomaly syndrome characterized by the variable combination of multiple anomalies, mainly Coloboma; Choanal atresia/stenosis; Cranial nerve dysfunction; Characteristic ear anomalies (known as the major 4 C's). "The next step will be to test if any mutations in the human FGF8 gene can contribute to cerebellar defects in CHARGE syndrome, and to investigate if any other developmental defects in CHARGE syndrome are associated with abnormal FGF8 levels." (PMID 24368733, 2013). "The altered cerebellar foliation pattern in Chd7 haploinsufficient mice show some similarities to those reported in mice with altered Engrailed, Fgf8 or Zic1 gene expression and we propose that mutations or polymorphisms in these genes may modify the cerebellar phenotype in CHARGE syndrome." (PMID 29168327, 2017). "The PUF60 gene, as well as CHD7, is considered responsible for CHARGE syndrome, which cooperatively translocates nucleosomes to permit transcription of FGF8 by RNA pol II in neural development." (PMID 32071290, 2020). "In CHARGE syndrome patients, protein interactions are spoiled in alternative splicing of FGF8 mRNA pre-mRNA processing in neural development due to dysfunction among BRG1, SWI/SNF and CHD7." (PMID 32071290, 2020). "These include the genes KAL1, FGFR1, FGF8 which encodes the ligand of FGFR1, PROKR2 and PROK2, NELF (nasal embryonic factor) and mutations in CHD7 associated with the CHARGE syndrome." (PMID 24204987, 2013). "Furthermore, the effect of FIRΔexon2 on FGF8 mRNA splicing was examined as an indicator of neural development due to impaired CHD7 revealed in CHARGE syndrome." (PMID 32071290, 2020).